SYDE1 (synapse defective Rho GTPase activating protein 1)
Description:
GTPase activator for the Rho-type GTPases. As a GCM1 downstream effector, it is involved in placental development and positively regulates trophoblast cells migration. It regulates cytoskeletal remodeling by controlling the activity of Rho GTPases including RHOA, CDC42 and RAC1.
Synonyms: 7h3; FLJ13511; SYD1
Tractability: PROTAC: ubiquitination databases record sites on it.
Gene: Protein-coding gene on chromosome 19 (15,107,364 to 15,114,988, forward strand). Ensembl gene ENSG00000105137.
Subcellular location (Human Protein Atlas): Nucleoplasm; Cytosol; Golgi apparatus
Pathways (Reactome):
Signal Transduction: CDC42 GTPase cycle; RAC2 GTPase cycle; RAC3 GTPase cycle; RHOF GTPase cycle; RHOJ GTPase cycle; RHOQ GTPase cycle
Gene Ontology:
Molecular function: GTPase activator activity; GTPase regulator activity
Biological process: actin cytoskeleton organization; cell migration; positive regulation of trophoblast cell migration; regulation of cytoskeleton organization; activation of GTPase activity; regulation of Ras protein signal transduction; signal transduction
Cellular component: synaptic membrane
Genetic constraint (gnomAD): Loss-of-function variants: 34 observed, 45.85 expected, observed/expected ratio (o/e) 0.74, 90% interval 0.56 to 0.99. The synonymous counts are far from expectation, so gnomAD's model fits this gene poorly and the ratio says little. Missense variants: 925 observed, 843.2 expected, observed/expected ratio (o/e) 1.1, 90% interval 1.04 to 1.16. Synonymous variants: 467 observed, 368.9 expected, observed/expected ratio (o/e) 1.27, 90% interval 1.17 to 1.37.
Homologues: Orthologues: chimpanzee SYDE1 (99% identical), macaque SYDE1 (97% identical), dog SYDE1 (91% identical), pig SYDE1 (90% identical), mouse Syde1 (87% identical), rat Syde1 (87% identical), rabbit SYDE1 (87% identical), guinea pig SYDE1 (86% identical), zebrafish SYDE1 (50% identical), Drosophila melanogaster RhoGAP100F (29% identical), Caenorhabditis elegans syd-1 (22% identical). Paralogues in human: SYDE2 (43% identical), ARHGAP35 (18% identical), CHN2 (13% identical), CHN1 (13% identical).
Diseases named in the same sentence as SYDE1 in open-access papers:
SYDE1 is named in the same sentence as 17 diseases in open-access papers, as found by Europe PMC text mining. Sharing a sentence is not in itself a finding about the gene and the disease. The quoted sentences say what the papers report.
cervical cancer (2 papers, 2014 to 2021). A primary or metastatic malignant neoplasm involving the cervix. "Moreover, SYDE1 has been revealed to be differentially expressed between cervical cancer and normal controls and is recognized as a potential causal gene related to cervical cancer." (PMID 34722629, 2021). "Methylated SYDE1 was demonstrated to be significantly associated with the relapse-free survival of patients with breast cancer However, there are currently no studies regarding the implications of SLURP1 and SYDE2 in cervical cancer." (PMID 25109897, 2014).
ovarian carcinoma (2 papers, 2015 to 2017). A malignant neoplasm originating from the surface ovarian epithelium. "Here, we designed small-scale siRNA screens targeting these six mesenchymal signature genes (CD99L2, EMP3, ITGA5, SYDE1, VIM, ZEB1) to explore their functional relevance and their roles during EMT reversal by nintedanib (BIBF1120) in a mesenchymal-like SKOV3 ovarian cancer cell line." (PMID 26061747, 2015).
renal cell carcinoma (2 papers, 2015 to 2021). "SYDE1 was included in a prognosis-associated 3-gene signature in renal cell carcinoma." (PMID 26061747, 2015).
Achalasia (1 paper, 2022). A disorder of esophageal motility characterized by the inability of the lower esophageal sphincter to relax during swallowing and by inadequate or lacking peristalsis in the lower half of the body of the esophagus. "Our study provides, for the first time, functional evidence about the PRKG1 gene as a direct target and SULF1 and SYDE1 as potential indirect substrates of miR-200c-3p and suggests the involvement of NO/cGMP/PKG signaling in the pathogenesis of achalasia." (PMID 36614110, 2022).
astrocytomas (1 paper, 2021). "In the GSE4290 and GSE4412_GPL96 datasets, the expression level of SYDE1 increased in the order of control of oligodendrogliomas, astrocytomas, and GBMs." (PMID 34722629, 2021).
cerebral tumors (1 paper, 2021). "Given the high expression level of SYDE1 in brain tissues, it is of great necessity to determine the function of SYDE1 in the pathogenesis of cerebral tumors, especially gliomas." (PMID 34722629, 2021).
glioma (1 paper, 2021). A benign or malignant brain and spinal cord tumor that arises from glial cells (astrocytes, oligodendrocytes, ependymal cells). "The TCGA, CGGA, and GEO cohorts also supported the result that high SYDE1 expression in gliomas is associated with shorter OS time, and decreased levels of SYDE1 expression are associated with longer OS time in glioma patients (p < 0.05)." (PMID 34722629, 2021). "As expected, individuals with increased SYDE1 in gliomas were associated with poor OS and DFS (p < 0.0001)." (PMID 34722629, 2021). "Initially, SYDE1 correlated with clinical parameters, and the expression levels of SYDE1 were significantly associated with glioma WHO grade." (PMID 34722629, 2021). "Based on these statistical results, SYDE1 can be considered an independent prognostic risk factor in gliomas, at least in part." (PMID 34722629, 2021). "In-depth elucidation of the functions of SYDE1 in gliomas, such as tumor formation in nude mice and population mutation screening, will provide a deeper understanding of the molecular pathology of gliomas." (PMID 34722629, 2021). "Overall, these findings confirm that SYDE1 expression is associated with different clinical outcomes and previous diagnostic biomarkers, which may benefit the diagnosis and treatment of gliomas." (PMID 34722629, 2021). "Another part of the data (CGGA mRNA-array_301, GSE4271, GSE13041_GPL96, and TCGA_glioma dataset) suggested that SYDE1 expression was significantly lower in the neural or PN subtypes (p < 0.05)." (PMID 34722629, 2021). "The aim of this study was to explore the association between synapse defective protein 1 homolog 1 (SYDE1) and gliomas via public database analysis and in vitro validation to determine the potential diagnostic and prognostic values." (PMID 34722629, 2021). "The GEPIA2 databases indicated that SYDE1 was expressed at higher levels in glioma subclasses LGG and GBMs than in the corresponding normal tissues (p < 0.05)." (PMID 34722629, 2021). "Higher microvascular proliferation and grade IV necrosis occurred with higher SYDE1 expression in gliomas (p < 0.05)." (PMID 34722629, 2021). "We used a comprehensive strategy for starBase 3.0, CGGA, and TargetScan databases to investigate the potential miRNA targets and the indirect lncRNAs targets of SYDE1 in gliomas." (PMID 34722629, 2021). "The protein expression pattern of SYDE1 in gliomas described by the Human Protein Atlas also helped account for this characteristic." (PMID 34722629, 2021). "Then, normal human brain and glioma samples from grades I to IV were collected for IHC staining of SYDE1, which revealed that SYDE1 expression is positively correlated with the clinical malignancies of glioma." (PMID 34722629, 2021). "In a similar manner, our data show that the expression of SYDE1 is higher in human glioma tissues, so it is reasonable to explore the biological function and molecular mechanism of SYDE1 in gliomas." (PMID 34722629, 2021). "Clinicopathological characteristics of patient samples and expression of SYDE1 in glioma and normal tissues." (PMID 34722629, 2021). "In our study, knockdown of SYDE1 in vitro significantly abolished the migration and invasion of glioma cell lines A172." (PMID 34722629, 2021). "First, we analyzed publicly published mRNA expression data of human glioma tissues and normal control tissues and found that SYDE1 expression was higher in gliomas than in healthy cerebral tissues." (PMID 34722629, 2021). "On the other hand, SYDE1 expression is higher in mouse glioma GL261 cells than normal C57BL/6 brains." (PMID 34722629, 2021). "Then, we performed RNAi-mediated SYDE1 knockdown in glioma cell lines in vitro, which revealed that SYDE1 knockdown abolished the migration and invasion of glioma cells." (PMID 34722629, 2021). "In summary, this study identifies SYDE1 as an oncogene in gliomas that can regulate the proliferation and migration of glioma cells and is predicted to interact with the SNHG16/hsa-miR-520e axis." (PMID 34722629, 2021).
glioma (continued). "In vitro knockdown of SYDE1 in glioma cell lines A172 inhibited their migrative and invasive ability but not the proliferative ability." (PMID 34722629, 2021). "Kyoto Encyclopedia of Genes and Genomes (KEGG) pathway analysis for predicted co-expression genes of SYDE1 in gliomas." (PMID 34722629, 2021). "In this study, we utilized publicly available data from the Oncomine, GEPIA2 and Human Protein Atlas (HPA) databases to examine SYDE1 expression in glioma tissues and normal control tissues, and we identified an increased level of SYDE1 in gliomas." (PMID 34722629, 2021). "Methods and Results: Compared with healthy brain tissues, there was a significant increase in SYDE1 expression in glioma tissues." (PMID 34722629, 2021). "For the histological subclasses, SYDE1 expression was highly associated with this category in the CGGA mRNA-array_301, CGGA mRNA-array_325, CGGA mRNA-array_693, TCGA_LGG, and TCGA_glioma databases (p < 0.05)." (PMID 34722629, 2021). "Considering that hsa-miR-520e is the target miRNA of SYDE1 with favorable outcomes in gliomas, the expression of the target lncRNAs (FGD5-AS1, MIR17HG, and SNHG16) of hsa-miR-520e was measured to calculate the prognostic ability of these signatures." (PMID 34722629, 2021). "Based on the correlation between SYDE1 expression and glioma revealed by bioinformatic analysis and IHC, we performed in vitro experiments to further verify this association." (PMID 34722629, 2021). "The analyzed data (CGGA mRNA_301, CGGA mRNA_325, and CGGA mRNA_693) indicated that glioma patients with the IDH_mutation attribute exhibited lower SYDE1 expression than patients with IDH_wildtype (p < 0.001)." (PMID 34722629, 2021). "We identified four analyses of upregulated SYDE1 between brain or CNS cancer and adjacent normal tissues in the Oncomine database that met the established threshold for |log2FC| >1.5, p < 0.01 and gene rank = all." (PMID 34722629, 2021). "Reactome pathways analysis for predicted co-expression genes of SYDE1 in gliomas." (PMID 34722629, 2021). "Positive staining of SYDE1 was predominantly found in grade IV glioma compared with grade I glioma." (PMID 34722629, 2021). "In addition, SYDE1 is more highly expressed in recurrent or necrotic gliomas or gliomas that occur in elderly patients." (PMID 34722629, 2021). "Association between SYDE1 expression and WHO grade in glioma." (PMID 34722629, 2021). "Our results showed that SYDE1 was more highly expressed in Mes subtypes than neural, PN, and Prolif subtypes based on CGGA mRNA-array_301, GSE4271, GSE13041_GPL96, and TCGA_glioma datasets (p < 0.05), but this association was not pronounced in GSE13041_GPL8300." (PMID 34722629, 2021). "Both databases support the hypothesis that SYDE1 is upregulated in CNS tumors, such as gliomas, versus normal tissues." (PMID 34722629, 2021). "We next report the SNHG16/hsa-miR-520e axis as a downstream target of SYDE1 in gliomas." (PMID 34722629, 2021). "In this study, we report the gene SYDE1 as a novel regulator of glioma tumors." (PMID 34722629, 2021). "Further bioinformatic analysis revealed that the SNHG16/hsa-miR-520e/SYDE1 axis might be involved in glioma development." (PMID 34722629, 2021). "Additionally, SYDE1 exhibited higher expression levels in glioma patients with unfavorable clinicopathological factors." (PMID 34722629, 2021). "After validation of the prognostic function of SYDE1 in gliomas, we further analyzed the existing data in the CGGA and TCGA databases to confirm whether it was an independent survival predictor in individuals with gliomas." (PMID 34722629, 2021). "To date, the role of SYDE1 in glioma development remains largely undetermined." (PMID 34722629, 2021). "Similarly, the 1p/19q codeletion demonstrated the same correlation, which means that SYDE1 expression was decreased in the 1p/19q_codeletion glioma samples compared with the corresponding 1p/19q_noncodeletion samples (p < 0.05)." (PMID 34722629, 2021).
glioma (continued). "To decipher the mechanisms of SYDE1 in glioma pathogenesis, we further constructed a coexpression network of genes in gliomas from the cBioPortal database whose Spearman’s correlation index values with SYDE1 rank in the top 100 and found that these genes were enriched in tumor-associated GO terms." (PMID 34722629, 2021). "We first observed that SYDE1 was highly expressed in gliomas, and an important, but unsolved, question is whether increased expression of SYDE1 is related to increasing glioma grade." (PMID 34722629, 2021). "Taken together, increased expression of SYDE1 in gliomas may lead to an overactivated transcriptional network that facilitates tumor invasion." (PMID 34722629, 2021). "Therefore, SYDE1 strongly correlated with WHO glioma grade at the mRNA and protein levels." (PMID 34722629, 2021). "Furthermore, SYDE1 has values in the diagnosis and prognosis prediction of gliomas." (PMID 34722629, 2021). "Furthermore, we also performed IHC to investigate SYDE1 expression in glioma tissue." (PMID 34722629, 2021). "Furthermore, SYDE1 expression was higher in HGGs than in LGGs, as revealed by bioinformatic analysis of the Gene Expression Omnibus (GEO), The Cancer Genome Atlas (TCGA) and Chinese Glioma Genome Atlas (CGGA) datasets." (PMID 34722629, 2021). "Therefore, it is tempting to speculate that SYDE1 expression correlates with glioma subtype." (PMID 34722629, 2021). "That is, upregulated SYDE1 in gliomas can potentially activate SNHG16 expression to facilitate the onset and progression of gliomas." (PMID 34722629, 2021). "SYDE1 expression significantly correlated with age in CGGA mRNA-array_325, CGGA mRNA-array_693, GSE4271, and TCGA_glioma (p < 0.05)." (PMID 34722629, 2021). "Notably, the expression of SYDE1 in older patients aged ≥45 years was higher than that in patients aged <45 years in the CGGA mRNA-array_301 (p < 0.05), CGGA mRNA-array_325 (p < 0.05), GSE4271 (p < 0.05), and TCGA_glioma datasets (p < 0.05)." (PMID 34722629, 2021).
intervertebral disc degeneration (1 paper, 2024). "The genes that are upregulated in the IVDD group, such as JUNB, SYDE1, ADAM8, and MAFB, are primarily involved in inflammatory responses, extracellular matrix remodeling, and cellular stress responses, which are processes known to be associated with intervertebral disc degeneration." (PMID 39430414, 2024).
liver fibrosis (1 paper, 2024). "Our previous studies have reported that SWT might improve liver fibrosis by regulating the expression of Myo1c, Syde1 and Rhoj in LSECs." (PMID 39741334, 2024).
lung carcinoma (1 paper, 2023). "SYDE1 is associated with epithelial–mesenchymal transition (EMT) reversal, which is associated with the progression of various tumors, including lung cancer." (PMID 37508851, 2023).
T-Cell Lymphoma (1 paper, 2017). "Based on these results and because of their novelty in this field, we further studied two targets that showed opposite effects on the barrier function: T-Cell Lymphoma Invasion And Metastasis 2 (TIAM2 - RhoGEF) and Synapse Defective1 (SYDE1 - RhoGAP)." (PMID 28860633, 2017).
cancer (3 papers, 2015 to 2025). A tumor composed of atypical neoplastic, often pleomorphic cells that invade other tissues. "However, the strategy to target SYDE1 is still elusive, as the understanding of its role(s) in human cancers is very limited." (PMID 26061747, 2015).
tumor (3 papers, 2021). "In the low SYDE1 expression group, tumor-associated terms “Hedgehog signaling” and “Kras signaling” were the enriched gene sets." (PMID 34722629, 2021). "GO and KEGG pathway analysis of the top 100 genes coexpressed with SYDE1 showed enrichments of tumor-associated terms." (PMID 34722629, 2021). "Moreover, GO and KEGG pathway analysis of SYDE1 coexpressed genes revealed an enrichment of tumor-associated terms, including protein serine kinase activity and focal adhesion." (PMID 34722629, 2021). "Additionally, four genes (i.e., COL6A1, SYDE1, ESCO2, and GIPC1) were differentially expressed between tumor and normal tissues." (PMID 34149809, 2021). "In addition, we have also identified a set of genes that are regulated in the opposite way by 7SK and FOXJ3/THRA, including four positive regulators in tumor migration (CXCL1, SYDE1, COL5A1, and HIF1A)." (PMID 33868377, 2021).
SYDE1 also shares sentences with these, for which no sentence is quoted: breast carcinoma (1 paper); CNS tumors (1); oligodendroglioma (1); preeclampsia (1).